LGR4 (leucine rich repeat containing G protein-coupled receptor 4)
Diseases named in the same sentence as LGR4 in open-access papers (continued):
Sharing a sentence is not in itself a finding about the gene and the disease.
thyroid cancer (4 papers, 2017 to 2022). "In thyroid cancer, upregulation of the LGR4/RSPO2 pathway leads to tumor aggressiveness, promoting cell proliferation and migration through the Wnt/β-catenin pathway and MAPK/ERK1/2 signaling." (PMID 33946652, 2021). "In this study, we demonstrated that exogenous RSPO2 treatment increased GPR48/LGR4-dependent ERK activation in thyroid cancer cells." (PMID 29383135, 2017). "We found that GPR48/LGR4 mRNA expression was markedly higher in the thyroid cancer cell lines TPC-1, BCPAP, and 8505C than in Nthy-ori3-1, a normal thyroid follicular cell line derived from a human adult." (PMID 29383135, 2017). "In this study, we obtained clear evidence of the functional expression of GPR48/LGR4 in thyroid cancer cells in vitro and in vivo." (PMID 29383135, 2017). "in vitro assays demonstrated that elevated expression of GPR48/LGR4 promoted proliferation and migration of thyroid cancer cells, whereas downregulation of GPR48/LGR4 decreased proliferation and migration by inhibition of the β-catenin pathway." (PMID 29383135, 2017). "R-spondin 2, and GPR48/LGR4 were expressed at significantly higher levels in thyroid cancer than in normal controls." (PMID 29383135, 2017). "To assess the effect of GPR48/LGR4 in tumorigenesis of differentiated thyroid carcinoma, we transfected a GPR48/LGR4 expression plasmid into TPC-1 and BCPAP, and investigated growth by CCK-8 viability assay and migration by Transwell assay." (PMID 29383135, 2017). "Based on this premise, we tested whether exogenous RSPO2 could directly increase β-catenin signaling, using a reporter assay and monitoring AXIN2 expression in control and GPR48/LGR4-knockdown thyroid cancer cells." (PMID 29383135, 2017). "The role of GPR48/LGR4 in proliferation and migration was examined in thyroid cancer cell lines." (PMID 29383135, 2017). "We investigated whether knockdown of GPR48/LGR4 decreased β-catenin signaling in thyroid cancer cells using the luciferase-based TOPflash/FOPflash assay." (PMID 29383135, 2017). "Moreover, treatment of thyroid cancer cells with exogenous R-spondin 2 induced activation of the β-catenin pathway through GPR48/LGR4." (PMID 29383135, 2017). "Thus, GPR48/LGR4 signaling may promote tumorigenesis by potentiating Wnt/β-catenin activity, which is elevated in thyroid cancer." (PMID 29383135, 2017). "To determine the mechanism by which GPR48/LGR4 promotes thyroid tumorigenesis, we monitored the ERK1/2 and β-catenin pathways in GPR48/LGR4-knockdown thyroid cancer cells." (PMID 29383135, 2017). "Given the elevated expression of GPR48/LGR4 in thyroid cancer tissue, we investigated the role of GPR48/LGR4 in proliferation and migration of thyroid cancer cells." (PMID 29383135, 2017). "Protein expression of GPR48/LGR4, as determined by Western blot analysis, was also higher in the thyroid cancer cell lines than in Nthy-ori3-1." (PMID 29383135, 2017). "In addition, elevated expression of GPR48/LGR4 promoted proliferation and migration of thyroid cancer cells, whereas downregulation of GPR48/LGR4 decreased proliferation and migration by inhibiting the β-catenin pathway." (PMID 29383135, 2017). "Based on these findings, we speculate that exogenous RSPO2 treatment can induce increased ERK1/2 phosphorylation in thyroid cancer cells, and that the effect of RSPO2 is strongly dependent on expression of GPR48/LGR4." (PMID 29383135, 2017). "Our findings demonstrate that upregulation of the R-spondin 2-GPR48/LGR4 pathway contributes to tumor aggressiveness in papillary thyroid carcinoma by promoting ERK phosphorylation, suggesting that this pathway represents a novel therapeutic target for treatment of differentiated thyroid cancer." (PMID 29383135, 2017). "For instance, GPR48/LGR4 overexpression promoted thyroid tumor growth, lymph node metastasis, and recurrence in vivo and proliferation and migration of thyroid cancer cells in vitro." (PMID 35535309, 2022).
type 2 diabetes (4 papers, 2022 to 2025). "Our study thus reveals LGR4 as a potential target to promote islet β cell flexibility for the intervention of type 2 diabetes." (PMID 40810739, 2025). "A critical question is whether the activation of LGR4 signaling can reverse insulin resistance, which could have significant implications for developing therapies to treat type-2 diabetes." (PMID 39033139, 2024). "These authors noted plasma LGR4 levels to decline with an increase in blood pressure in the hypertension-suffering subjects with type 2 diabetes, as compared to their non-hypertensive counterparts." (PMID 35707461, 2022).
cataract (3 papers, 2015 to 2023). Partial or complete opacity of the crystalline lens of one or both eyes that decreases visual acuity and eventually results in blindness. "LGR4-deficient mice are prone to develop cataracts, showing early onset of lens opacification and a higher incidence of cataract formation." (PMID 33946652, 2021). "One study showed that one in four Lgr4 knockout mice are affected by cataracts, with disorganized and enlarged lens fibres at the cortex of the lens." (PMID 37118843, 2023). "In this study, we first verified that Lgr4 null mice had early onset of cataracts, along with description of their phenotype with regards to the cataracts." (PMID 25811370, 2015). "Since deletion of Lgr4 has previously been shown to lead to cataract formation in mice, we sought to determine the specific role that Lgr4 plays in the formation of cataracts." (PMID 25811370, 2015). "Previously, we have described that about 26% of Lgr4 knockout mice have cataracts, lens fiber disorganization and abnormal protein deposition in lenses." (PMID 25811370, 2015). "As lens epithelial cells play important roles in the development of cataracts, we investigated the detailed expression profile of Lgr4 in lens epithelial cells." (PMID 25811370, 2015). "Another study found that Lgr4 knockout mice developed lens opacities earlier than wild type mice after exposure to oxidative stressors and had an increased incidence of cataracts, which indicate that Lgr4 may play an important role in cataract formation." (PMID 37118843, 2023). "Furthermore, LGR4 also participates in the induction of cataracts mediated by let7-b." (PMID 33946652, 2021). "Homozygous Lgr4−/− mice with nontransparent lens accounted for about 47.3% (53/112) of total mutant adults, whereas only 17.7% (29/164) wild-type mice showed cataracts." (PMID 25811370, 2015).
endometritis (3 papers, 2021 to 2025). An acute or chronic, usually bacterial infectious process affecting the endometrium. "Another experimental endometritis model also reports LGR4 as a miRNA target." (PMID 41333132, 2025). "Therefore, miR-193a-3p was shown to induce an inflammatory response by targeting LGR4 and subsequent production of IL-1β, IL-6, and TNF-α, as presented in an experimental model of endometritis." (PMID 41333132, 2025).
hepatocellular carcinoma (3 papers, 2022 to 2025). A malignant tumor that arises from hepatocytes. "Beyond APC-driven metabolic shifts, leucine-rich repeat-containing G protein-coupled receptor 4 (LGR4), a receptor in the Wnt pathway, promoted metabolic reprogramming in hepatocellular carcinoma (HCC) by enhancing glycolysis and lactate production." (PMID 40917745, 2025). "Although the study indicated that Hsa_circ_0003945 could regulate the miR-34c-5p/LGR4/β-catenin axis to promote the progression of hepatocellular carcinoma, the exact role of LGR4 is still unclear." (PMID 36385965, 2022).
Infertility (3 papers, 2014 to 2024). "Poor to zero sperm motility and infertility were also observed in the Lgr4 null (Lgr4−/−) and hypomorphic (Lgr4Gt/Gt) mutant male mice." (PMID 38500604, 2024). "Infertility of Lgr4 mutant males was owing to the combination of a developmental defect of the epididymal head and the rupture of the epithelium resulting in decreased motility and abnormal morphology of spermatozoa." (PMID 38500604, 2024). "Therefore, the testicular effects of Lgr4 on controlling the Esr1 expression might potentially explain the consequence of infertility in Lgr4-null mice." (PMID 25188337, 2014).
melanoma (3 papers, 2020 to 2023). A malignant, usually aggressive tumor composed of atypical, neoplastic melanocytes. "LGR4 is over-expressed in melanoma cells; however, it is barely expressed in squamous and basal cell carcinomas." (PMID 33946652, 2021). "LGR4 plays crucial roles in skin carcinogenesis and melanoma development." (PMID 33946652, 2021). "Overexpression of mir-34a attenuates migration, invasion, and EMT by decreasing LGR4 expression, which regulates the expression of the matrix metalloproteinase 2 (MMP2) in melanoma cell lines." (PMID 33946652, 2021).
myocardial infarction (3 papers, 2021 to 2025). Gross necrosis of the myocardium, as a result of interruption of the blood supply to the area, as in coronary thrombosis. "In the experimental model of myocardial infarction, it has been shown that LGR4 potentiates inflammatory modulation of infarct macrophages through AP (activator protein)-1-CREB pathway activation." (PMID 41333132, 2025). "Studies with macrophage-specific Lgr4 knockout mice (Mac-L4KO) have shown improved cardiac function and a modest reduction in infarct size, suggesting that targeting macrophage Lgr4 could be a potential therapeutic strategy for myocardial infarction." (PMID 40895433, 2025). "Targeting LGR4 macrophages might be suitable for early therapeutic interventions to attenuate myocardial injury and enhance wound healing following acute myocardial infarction." (PMID 41333132, 2025).
polycystic kidney disease (3 papers, 2014 to 2023). A usually autosomal dominant and less frequently autosomal recessive genetic disorder characterized by the presence of numerous cysts in the kidneys leading to end-stage renal failure. "Similar to the phenotype of AGR syndrome, whole-body deletion of Lgr4 in mice led to aniridia, polycystic kidney disease, genitourinary anomalies, and mental retardation." (PMID 36538378, 2023).
uveal melanoma (3 papers, 2021). A melanoma derived from melanocytes of the uveal tract. "Its overexpression decreases migration and invasion of uveal melanoma cells through targeting LGR4 and regulation of EMT process." (PMID 33968718, 2021). "MiR-34a negatively controlled the expression level of LGR4, thus downregulating the markers of the EMT and MMP2, thereby impacting the aggressiveness of uveal melanoma." (PMID 35140734, 2021). "It has been shown that miR-34a/LGR4 targets MMP2 to mediate EMT, thus regulating migration and invasion of uveal melanoma cells." (PMID 34852712, 2021).
Age-related cataract (2 papers, 2016 to 2021). A type of cataract (opacification of the lens) that forms during the course of aging. "A targeted deletion in LGR4 reduced the resistance of rat lens epithelial cells to oxidative stress and accelerated the development of age-related cataracts." (PMID 34706646, 2021).
atherosclerosis (2 papers, 2024 to 2025). A disease characterized by the build-up of fatty material and calcium deposition in the arterial wall resulting in partial or complete occlusion of the arterial lumen. "Future studies are warranted to discover the other potential receptors of NID2 and investigate atherosclerosis in mice with cell-specific Lgr4 deletion combined with NID2 overexpression to clarify the role of the NID2-LGR4 axis in atherogenesis." (PMID 39684493, 2024). "Therefore, inhibition of Rspo2-induced LGR4 activation and downstream Wnt signaling utilizing recombinant proteins, blocking antibodies, and small molecule inhibitors has the potential to reduce atherosclerosis; however, this possibility requires further investigation." (PMID 41300494, 2025).
breast tumor (2 papers, 2022). "Our IHC staining results confirmed that the expression level of LGR4 was significantly higher in human bone metastatic tumor samples (n = 27) compared with primary breast tumor samples (n = 73)." (PMID 34847079, 2022).
CNS demyelinating disease (2 papers, 2017 to 2021). "In contrast, patients with coexisting CNS demyelinating disease and hyperthyroidism showed significantly increased T cell responses to a panel of three LGR4 peptides, compared to all other groups (p ≤ 0.005)." (PMID 28533776, 2017). "However, even with the limited number of peptides used, we could still see significantly elevated responses to LGR4 in the subgroup of patients with coexisting AITD and CNS demyelinating disease." (PMID 28533776, 2017). "In this paper, we report that patients with coexisting CNS demyelinating disease and AITD show novel immune reactivity to CGRP and LGR4 which is not found in MS patients who do not have AITD and HC." (PMID 28533776, 2017).
colitis (2 papers, 2015 to 2025). Inflammation of the colon. "Histological examination showed dramatically increased signs of colitis, which is characterized by the loss of crypts and the infiltration of leukocytes into the colons of Lgr4 mutant mice." (PMID 26379625, 2015). "For example, it has been found that LGR4 exerts protective effects from DSS-induced colitis in the mouse experimental model." (PMID 41333132, 2025). "When Lgr4 hypomorphic mice are subjected to the dextran sulfate sodium (DSS)-induced IBD, a more severe colitis developed in Lgr4 mutant mice than in WT sex-matched littermates." (PMID 26379625, 2015).
glioma (2 papers, 2014 to 2021). A benign or malignant brain and spinal cord tumor that arises from glial cells (astrocytes, oligodendrocytes, ependymal cells). "So far no information is available on LGR4 expression in gliomas." (PMID 24662753, 2014).
leukemia (2 papers, 2021 to 2026). A malignant (clonal) hematologic disorder, involving hematopoietic stem cells and characterized by the presence of primitive or atypical myeloid or lymphoid cells in the bone marrow and the blood. "RSPO3/Lgr4 upregulates WNT/self-renewal target genes to block differentiation, which contributes to the aggressive leukemia phenotype, probably through the pCREB-CBP complex." (PMID 33946652, 2021).
liver fibrosis (2 papers, 2025). "By contrast, MASLD and ALD, against which RSPO3, LGR4/5 and their downstream target β-catenin protect, represent the commonest forms of CLD and liver fibrosis in patients." (PMID 40074890, 2025).
microphthalmia (2 papers, 2013 to 2021). Congenital or developmental anomaly in which the eyeballs are abnormally small. "Could Norrin be the unknown sex-linked factor responsible for the higher incidence of microphthalmia in male Lgr4−/− mice?" (PMID 23840940, 2013).
serous ovarian cancer (2 papers, 2021 to 2023). "LGR4/ELF3 axis could also enhance the epithelial phenotype of serous ovarian cancer and was mediated by WNT7B/FZD5 interaction." (PMID 35140734, 2021). "In high-grade serous ovarian cancer (HGSOC), ELF3 forms a positive feedback loop with LGR4, which is involved in stem-cell renewal." (PMID 36864480, 2023).
squamous cell carcinoma of the skin (2 papers, 2013 to 2017). "Haplotype insufficiency of LGR4 in human was associated with several diseases, including increased risk of squamous cell carcinoma of the skin, reduced birth weights, electrolyte imbalance, and decreased levels of testosterone, which are similar to the phenotypes of LGR4-hypomorphic mice." (PMID 24205130, 2013). "Loss of either RSPO1 or LGR4 increases the risk of developing squamous cell carcinoma of the skin, indicating that RSPO1-LGR4 signaling plays a vital role in the negative regulation of cell proliferation in the skin." (PMID 24205130, 2013). "The strong expression of LGR4 in basal and granular cells is consistent with the findings that LGR4 plays a critical role in these cells as loss of LGR4 or RSPO1 led to increased risk of squamous cell carcinoma of the skin in human." (PMID 24205130, 2013).
alopecia (1 paper, 2013). Hair loss usually from the scalp. "Mice with specific ablation of Lgr4 in cells expressing keratin 5 showed focal alopecia and fewer hair placodes, implicating Lgr4 action in hair follicle development." (PMID 23840940, 2013).
autoimmune disease (1 paper, 2017). A disorder resulting from loss of function or tissue destruction of an organ or multiple organs, arising from humoral or cellular immune responses of the individual to their own tissue constituents. "The number of patients in the current study is too small to determine whether elevated reactivity to CGRP and/or LGR4 definitely correlates with the development of other autoimmune diseases affecting the gastrointestinal tract or skin, but this would be an interesting study for the future." (PMID 28533776, 2017).
Axenfeld-Rieger syndrome (1 paper, 2013). Axenfeld-Rieger syndrome (ARS) is a generic term used to designate overlapping genetic disorders, in which the major physical condition is anterior segment dysgenesis of the eye. "Several lines of evidence implicate the Axenfeld-Rieger syndrome-related gene Pitx2 as a key mediator of Lgr4 in eye development." (PMID 23840940, 2013).
Bone metabolic disorders (1 paper, 2025). "LGR4 has great potential in the treatment of bone metabolic disorders." (PMID 40469438, 2025).
central obesity (1 paper, 2025). "Human genetic analysis has identified the gain-of-function variant of LGR4, LGR4 A750T variant, as a genetic determinant of central obesity." (PMID 40069508, 2025).
cervical cancer (1 paper, 2014). A primary or metastatic malignant neoplasm involving the cervix. "Expression of LGR4 was also associated with invasiveness and metastatic activity of colon and cervical cancer cells." (PMID 24662753, 2014).
colon adenocarcinoma (1 paper, 2022). "Our investigation revealed that LGR4 can be an emerging diagnostic and prognostic biomarker for colon adenocarcinoma by affecting metabolism-related pathways." (PMID 36008975, 2022). "Further functional analysis demonstrated that higher expression of LGR4 in colon adenocarcinoma may be linked to up-regulate metabolism-related pathways, for example, the cholesterol biosynthesis pathway." (PMID 36008975, 2022). "Kaplan–Meier analysis revealed that higher expression of LGR4 correlates with overall survival of colon adenocarcinoma patients, although expression levels of LGR4 in normal tissues are higher than in tumor tissues." (PMID 36008975, 2022). "After identifying the differentially expressed genes among colon adenocarcinoma tissues with different expression levels of LGR4 and normal tissue, protein–protein interaction, gene ontology, pathway enrichment, gene set enrichment analysis, and immune cell infiltration analysis were conducted." (PMID 36008975, 2022).
cutaneous melanoma (1 paper, 2023). A primary melanoma arising from atypical melanocytes in the skin. "In our study, RSPO1 and RSPO3 were identified as important stroma-to-tumor ligands, each interacting with both the LGR4 and LRP6 receptors in cutaneous melanoma." (PMID 36676129, 2023).
cyst (1 paper, 2012). A sac-like closed membranous structure that may be empty or contain fluid or amorphous material. "Organoids grew as cyst-like structures without crypts, similar to the initial growth of Lgr4/5-deficient organoids treated with CHIR99021." (PMID 22815884, 2012).
cystic kidney disease (1 paper, 2022). A congenital or acquired kidney disorder characterized by the presence of renal cysts. "Pkd1, Pkd2 and Lgr4, genes involved in cystic kidney disease are now also known to play a role in Wolffian duct coiling." (PMID 35735916, 2022).
deafness (1 paper, 2023). An inherited or acquired condition characterized by the complete loss of the ability to hear from one or both ears. "However, studies of LGR4 variants in patients and of whole-body Lgr4-KO mice demonstrated the association between LGR4 alterations and fetal/perinatal death, short stature, deafness, and dysplastic nails." (PMID 36538378, 2023).